RNU7-181P (RNA, U7 small nuclear 181 pseudogene)
Gene: Small nuclear RNA gene on chromosome 8 (130,004,528 to 130,004,601, reverse strand). Ensembl gene ENSG00000253043.
Homologues: Orthologues: macaque U7 (61% identical). Paralogues in human: RNU7-70P (69% identical), RNU7-62P (68% identical), RNU7-152P (66% identical), RNU7-18P (66% identical), RNU7-21P (66% identical), RNU7-148P (65% identical), RNU7-171P (65% identical), RNU7-20P (65% identical), RNU7-2P (65% identical), RNU7-35P (65% identical), RNU7-55P (65% identical), RNU7-57P (65% identical), and 142 more.